HIF1A (hypoxia inducible factor 1 subunit alpha)
Diseases named in the same sentence as HIF1A in open-access papers (continued):
Sharing a sentence is not in itself a finding about the gene and the disease.
tumor (continued). "In addition, HIF-1a upregulates the expression of nuclear factor-kβ and leads to increased recruitment of monocytes and tumor-associated macrophages (TAMs), including polarization of the M2 phenotype TAMs, which promotes recurrence and metastasis." (PMID 35281003, 2022). "HIF-1α overexpression in tumor tissues is frequently associated with poor prognosis, implying that HIF-1α may have utility as a biomarker for assessing tumor treatment efficacy and prognosis, as well as a possible therapeutic target." (PMID 36139386, 2022). "Genetical changes and uncontrolled cancer growth, which generate intra-tumor hypoxic areas (used by the innovative hypoxia-responsive drug delivery nanoplatforms), cause HIF-1α overexpression enhancing neo-angiogenesis through VEGF synthesis and therefore favoring cancer progression and metastasis." (PMID 36613522, 2022). "Tumour-associated CpG demethylation might represent a mechanism of epigenetic autoregulation of HIF-1α expression." (PMID 35887244, 2022). "Additionally, HIF-1α stands out as a mediator of tumor-promoting inflammation in H. pylori and EBV-associated GCs, implying its involvement in gastric carcinogenesis." (PMID 35681691, 2022). "Moreover, the expression of HIF-1α and Ki67 was reduced in tumor cells, which caused the tumor's morphology and structure to be destroyed." (PMID 35933373, 2022). "Previous studies have confirmed that in the hypoxic environment of tumors, HIF1α promotes the remodeling of extracellular matrix, induces the recruitment of tumor-associated macrophages (TAM) and immunosuppression of allogeneic tumors, thereby influencing tumor recurrence and metastasis." (PMID 36473847, 2022). "Similarly, hypoxia, and in particular HIF-1α, drives the differentiation of myeloid-derived suppressor cells (MDSCs) into tumor-associated macrophages (TAMs), which guides cancer treatment." (PMID 35574385, 2022). "High expression of HIF-1α showed a significant association with tumor size (OR=1.392." (PMID 35845307, 2022). "The complexities of cancer prognosis (the high variability of tumor mutations, histological types, grades and stages) make it too simplistic to think that the levels of expression of a single gene such as HIF1A might have a significant impact on prognosis." (PMID 35629169, 2022). "The silencing of TIA proteins in several tumor cell lines triggers the upregulation of HIF-1α expression, and rapid and severe hypoxia causes co-aggregation of TIA proteins, which suppress HIF-1α expression, reflecting the control of HIF-1α expression by TIAR/TIA1." (PMID 35887183, 2022). "Standard statistical methods (Pearson chi-square test, Fisher exact test, Kruskal–Wallis test, Mann–Whitney test and Kaplan–Meier method) were used to study the association of HIF-1α with tumor response, survival and other clinicopathologic variables/biomarkers." (PMID 36358811, 2022). "Furthermore, the association of SDH mutations with activation of HIF1α or HIF2α, or of both transcription factors together, has been a subject of debate with conflicting published data in cell lines and tumor tissues." (PMID 35740651, 2022). "Furthermore, tumor-associated long noncoding RNAs (lncRNAs) play pivotal roles in HIF1A pathway regulation and tumor immune escape." (PMID 35659268, 2022). "For example, in macrophages activated by inflammatory stimuli and in tumor-associated macrophages, normoxic stabilization of HIF-1α may be induced by metabolites, including succinate and lactate." (PMID 36496973, 2022). "Based on this hypothesis, this review summarizes the role of metabolic changes caused by HIF-1α/ERRα in the metabolic reprogramming of tumor cells in the growth, invasion, and metastasis of EC." (PMID 35800058, 2022).
tumor (continued). "In an established tumor, like those used to create the cell lines used in xenograft studies, HIF1α may suppress tumor growth and/or metastasis, and the loss of HIF1α therefore may induce worse prognoses." (PMID 36040300, 2022). "A second aim was to investigate whether tumour hypoxia and HIF-1α accumulation are associated with IBTR." (PMID 35140341, 2022). "A further understanding of the mechanisms underlying HIF-1α-independent induction of VEGF may provide therapeutic strategies for controlling angiogenesis enhanced by factors of the tumor microenvironment, such as BM-MSC secretions." (PMID 36230633, 2022). "The HIF1A A588T SNP was associated with total metabolic tumour volume (TMTV) and time-to-progression, with significantly lower TMTV (median 16 cm3, IQR 7–210, versus 146 cm3, IQR 34–510; p = 0.034) and longer time-to-progression in minor allele carriers (log-rank p = 0.094)." (PMID 34708297, 2022). "Taken together, these results indicate that HIF1A expression in tumor-associated macrophages induces IL-23 secretion, which may suppress T cell immune functions through Tregs." (PMID 35659268, 2022). "Additionally, HIF1A upregulates expression of tumor-associated long noncoding RNAs and suppresses immune cell function, enabling tumor immune escape." (PMID 35659268, 2022). "However, high-dose irradiation also induces immune suppression by causing vascular damage, increasing tumor hypoxia, and upregulating hypoxia-inducible factor-1α (HIF-1α), the master transcription factor for oxygen homeostasis and immune suppression." (PMID 35805044, 2022). "It was hypothesized that FAM13A together with HIF1α might be associated with antitumor effector T cells in the control area surrounding the growing tumor, in which oxygen deprivation occurred." (PMID 33919074, 2021). "However, the underlying molecular mechanism of HIF-1α’s contributions to drug resistance is complicated, multiple, and specific in some tumor types." (PMID 34950650, 2021). "We also speculate that the level of ID1 will be inversely associated with HIF1α in clinical tumor samples." (PMID 34820369, 2021). "Then, DEC2 may associate with HIF1α in contributing to tumor dormancy, which might provide a possible cue to explain the different roles of DEC2 in primary and metastasis lesions." (PMID 33990215, 2021). "Low intensity NIR irradiation of infiltrated tumors resulted in alterations of the tumor microenvironment, and more specifically in reducing HIF-1α factor associated with tumor survival, metastasis, and angiogenesis, whereas high intensity irradiation showed high cytotoxicity in tumor cells." (PMID 33408768, 2021). "Furthermore, previous studies suggested that HIF-1α was associated with tumor metastasis, promoting cell migration and invasion." (PMID 33748142, 2021). "Loss of HIF1α in NK cells inhibited tumour growth despite attenuated cytotoxicity." (PMID 34090499, 2021). "In our pursuit to maintain the balance of macrophage phenotypes to eliminate malignant tumor cells, we emulated a theoretical genetically modified macrophage by modifying the activation of NFκB and a loss of function in HIF1-α and discussed their phenotype implications." (PMID 34177892, 2021). "However, it has also been proposed that HIF-1α deletion is likely to cause pleiotropic effects, for example, affecting the release of tumor suppressive pathways and accelerating PC growth." (PMID 33436044, 2021). "Interestingly, a study has reported that HIF-1α overexpression in tumor cells takes part in an autocrine growth factor loop, which involves the HIF-1α-dependent expression of genes encoding IGF-2, IGFBP-2 and IGFBP-3." (PMID 33467713, 2021). "In addition, tumor-associated hypoxia via HIF1α upregulates the programmed cell death ligand PD-L1 on MDSCs, a modulation crucial for T cell suppression activity." (PMID 33923299, 2021). "However, hypoxia-inducible factor 1a (HIF-1α) plays a critical role in the function of tumor-associated macrophages (TAMs)." (PMID 34716294, 2021).
tumor (continued). "In support of this speculation, enforced HIF-1α expression restored the invasiveness of Prak-deficient tumor cells." (PMID 33741957, 2021). "Hypoxia is a key concern during the treatment of non-small cell lung cancer (NSCLC), as with pulmonary metastasis of OSCC, and hypoxia-inducible factor 1 alpha (HIF-1α) has been associated with increased tumor resistance to therapeutic agents such as cisplatin." (PMID 34039370, 2021). "Loss of EGFR or HIF1α abrogates Th9 cell differentiation and suppresses their anti-tumor functions." (PMID 34075041, 2021). "Additionally, elevated HIF-1α levels are associated with decreased miR-548a, and thus enhance glycolysis and tumor growth." (PMID 33401572, 2021). "Notably, treating Parkin-deficient cancer cells with small-molecule HIF-1α inhibitors greatly suppresses tumorigenesis of cancer cells in xenograft tumor models." (PMID 33681231, 2021). "Interestingly, while we expected Vhl deletion to yield the opposite tumor growth pattern from Hif1α deletion and cause tumors to grow more rapidly, Vhl-deleted tumors in fact progressed more slowly." (PMID 34556788, 2021). "The significance of this is unclear, but HIF-1α has been reported to act as a tumour suppressor in VHL-associated renal clear cell carcinoma, and it may be that HIF-1 also has a tumour suppressive role in this context." (PMID 34658364, 2021). "Moreover, carbonic anhydrase IX, a hypoxia-induced enzyme, is related to HIF-1α activity, as its overexpression is associated with poor prognosis in a variety of tumours, especially neuroblastoma." (PMID 34256803, 2021). "HIF-1α accumulates under hypoxic conditions and is associated with tumor progression." (PMID 34975472, 2021). "Interestingly, we show direct killing of GAS by NK cells in a HIF-1α-dependent manner and this is in line with a previous report on impaired tumour cell killing by HIF-1α-deficient NK cells." (PMID 34349124, 2021). "Perfusion-restricted hypoxia (also called acute hypoxia) mainly mediated by HIF-1α causes constant fluctuations leading to cyclic periods of hypoxia and re-oxygenation that can lead to the development of a heterogeneous cell population within the tumor." (PMID 33639646, 2021). "Mutations of VHL can cause HIF1α stabilization, inducing sustained tumor angiogenesis." (PMID 34117220, 2021). "It is therefore imaginable that tumor-associated NO modulates HIF-1α abundance in tumors." (PMID 34671319, 2021). "Similarly, worse overall and disease-free survival of lung cancer patients was associated with high levels of HIF-1α, glucose transporter I and CA-IX detected in tumour tissues." (PMID 34829672, 2021). "Besides, histone deacetylase inhibitor (HDACi) mitigates tumor growth via targeting HIF-1α, whereas underlying mechanism still requires investigation." (PMID 34329303, 2021). "Tumor re-proliferation was associated with early HIF-1α and later HIF-2α activations." (PMID 34824343, 2021). "It has been demonstrated that tumor-associated macrophages (TAMs) enhance aerobic glycolysis and apoptotic resistance in BC cells via the transmission of extracellular vesicles (EV) that contain a myeloid-specific HIF-1α-stabilizing long noncoding RNA (HISLA)." (PMID 33718202, 2021). "In addition to promote vascularization of the tumor mass, HIF1α had also been linked to the generation of CSCs through upregulation of glycolysis and the expression of a number of stemness genes." (PMID 35052581, 2021). "Therefore, up-regulated expression of HIF-1α has been shown to augment tumor angiogenesis, promote tumor cell proliferation and has been associated with poor prognosis." (PMID 35127500, 2021). "At the level of the tumor microenvironment, hypoxia in turn causes an increased basal metabolism of the cancer cell which, consequently, becomes able to self-feed the same hypoxia, especially through activation of the hypoxia inducible factor 1 α (HIF-1α)." (PMID 34205678, 2021).
tumor (continued). "Turning off HIF1-α increased phenotypes associated with tumoricidal capacity (M1 and M1M2b), denoting the importance of not expressing these transcriptional factors for eliminating tumor cells." (PMID 34177892, 2021). "HIF1α is a transcriptional factor regulated by hypoxic microenvironment but also by other factors such as oncogene activation or loss of tumor suppressors Overexpression of HIF1α in the hypoxic environment promotes the upregulation of glucose transporters and glucose enzymes." (PMID 33799793, 2021). "Additionally, hypoxia promotes the differentiation of MDSCs into immune suppressive tumor-associated macrophages (TAMs) in a HIF-1α-dependent manner, further supporting the establishment of an immunosuppressive network." (PMID 33422072, 2021). "Secondly, the role of FAP may be contrary to that of loss of HIF‐1α, leading to the promotion of tumour growth." (PMID 33943003, 2021). "However, nuclear or cytoplasmic expression of HIF-1A appears to be associated with some clinical features including tumor size and differentiation." (PMID 33403040, 2021). "Tumor hypoxia or pVHL loss will lead to the accumulation of HIF1α." (PMID 34779768, 2021). "The bulk of research on HIF-1α concerns crucial aspects of cancer biology; hypoxia, which is a hallmark feature of the tumor microenvironment, promotes protein stability of HIF-1α subunit by inhibiting the activity of PHDs, as they require oxygen to hydroxylate HIF-1α." (PMID 34572324, 2021). "Thus, IDH1 has been suggested to act as a tumor suppressor, which, when inactivated by mutation, contributes to tumorigenesis in part by induction of the HIF-1α pathway." (PMID 34073734, 2021). "By using the B16-F10 melanoma model, we obtained results that demonstrate that the regulatory axis between Bmal1 and Hif-1α dictates macrophage energy investment that is relevant for discrete activation or polarization states, including activation of M1 and tumor-associated macrophages." (PMID 32396064, 2020). "Anti-angiogenic therapy causes hypoxia which results in the activation of HIF1a in tumor cells." (PMID 32175278, 2020). "Given the major role of HIF-1α in compensating for oxygen deficiency by increasing availability of oxygen or providing metabolic adaptation of tumor cells, the inhibition of this activity might provide a potential approach to FMGC treatments." (PMID 32375802, 2020). "Furthermore, miR-200b was associated with reduced p-AKT, p-ERK1/2, and HIF-1α in excised tumor samples." (PMID 32435616, 2020). "Indeed, immune deconvolution analyses revealed that the group of tumours that exhibit loss of one copy of HIF1A or that show high levels of mRNA expression of HIF2A show many differences in signatures of different types of cells in the immune microenvironment." (PMID 32807776, 2020). "In fact, there is a relationship between NF-κB and tumor progression-associated inflammation that controls the expression of cancer-associated genes such as cytokines, chemokines, growth factors, and transcription factors such as HIF-1α." (PMID 33374961, 2020). "For example, expression of HIF1A in tumor-associated macrophage (TAM) might suppress T cell function." (PMID 32457841, 2020). "Considering a half of the tumor‐driven pVHL mutations harbor in α domain of pVHL, which interferes with its ability to bind elongin C and leads to the loss of pVHL protein stability, we propose that OTUD6B overexpression resists HIF‐1α accumulation in tumor cells with pVHL α domain mutations." (PMID 32328410, 2020). "Similarly, in the nutrient-deprived tumor microenvironment, tumor-derived lactate has been proposed to increase Hif-1α activity in tumor-associated macrophages (TAMs) and thus to upregulate Arg1." (PMID 32396064, 2020).
tumor (continued). "Moreover, a recent study has demonstrated that cancer cells also secrete succinate to activate the succinate receptor and HIF-1α signaling axis in tumor-associated macrophages (TAMs) that can control M2 polarization and immunosuppression for tumorigenesis." (PMID 32121028, 2020). "The presence of hypoxia in the tumor environment can generate CSCs and cause acquisition of radiotherapy-resistance, and under hypoxic conditions, HIF-1α and LOX are stabilized and secreted, respectively, and mediate premetastatic niche formation to promote cancer metastasis." (PMID 33126606, 2020). "EMT is initiated by HIF-1α-Snail axis activation, causing tumor cell invasion and migration." (PMID 33062005, 2020). "The TCGA data set analysis indicated that HIF1α expression may be closely associated with LUAD tumor progression." (PMID 32439898, 2020). "FIH1, which blocks the interaction between HIF-1α and CBP/p300, is validated to be downregulated because of a corresponding miRNA deficiency in tumors, consequently suppressing the tumor hypoxia response and angiogenesis by suppressing HIF-1α transcription and VEGF production." (PMID 32014012, 2020). "In addition to CNV, molecular research has demonstrated that the transcription factor HIF1A drives tumor growth and metastasis, and is associated with poor prognosis in BRCA." (PMID 33234738, 2020). "However, we have only a few stage I and stage IV tumor samples, thus, the observed association of HIF-1α expression is specific to stage II and stage III and the observed findings need to be validated with a larger sample set." (PMID 32707933, 2020). "Activation of mammalian target of rapamycin (mTOR) and loss of tumor suppressors like LKB1 may activate HIF-1 by enhancing HIF-1α protein synthesis." (PMID 32531951, 2020). "Also, nuclear HIF-1α expression was associated with the presence of necrosis, larger tumor size, low microvascular density, and shorter survival." (PMID 33537001, 2020). "Herein we show by introducing floxed alleles of Hif1a or Hif2a into an autochthonous mouse model of ccRCC that HIF-1α is necessary for tumour formation whereas HIF-2α deficiency has only a moderate effect on tumour initiation and growth." (PMID 32807776, 2020). "HIF-1α alters the metabolism of tumor cells, causes the release of the proangiogenic factors vascular endothelial growth factor (VEGF), N-myc downstream regulated 1 (NDRG1) and Glucose transporter 1 (GLUT1), promotes cell proliferation and inhibits cell apoptosis." (PMID 32312328, 2020). "HIF-1α is also considered to be a key molecule in the transactivation of genes implicated in altered metabolism, leading to the accumulation of several types of metabolites in the microenvironment that promote tumor growth and aggressiveness." (PMID 32823915, 2020). "By implicating Nrf2 in hypoxia-induced drug resistance and providing evidence for direct interaction of Nrf2 protein with HIF-1α enhancer, our study has gained significant insights into the underlying mechanisms by which the hypoxic tumor micro-environment causes chemo-resistance." (PMID 33290263, 2020). "Dual blockade of PD-L1 and HIF-1α could further reduce the glycolytic activity of cancer cells caused by PD-L1 blockade and enhance anti-tumor immunity, ultimately leading to cancer cell death." (PMID 33193345, 2020). "As a result, loss of HIF-1α decreased tumor vascularization." (PMID 31106156, 2019). "HIF-1α acts as an important transcriptional regulator directly or indirectly associated with genes involved in cell proliferation, angiogenesis, apoptosis and energy metabolism during tumor progression in hypoxic microenvironment." (PMID 30876462, 2019).